OMG (oligodendrocyte myelin glycoprotein)
Description:
Cell adhesion molecule contributing to the interactive process required for myelination in the central nervous system.
Synonyms: OMGP; LOC101927057
Tractability: Antibody: its Gene Ontology location is reachable by antibodies, with high confidence; UniProt places it where antibodies can reach, with medium confidence; UniProt predicts a signal peptide or a membrane-spanning region. PROTAC: its protein half-life has been measured.
Gene: Protein-coding gene on chromosome 17 (31,272,013 to 31,297,539, reverse strand). Ensembl gene ENSG00000126861.
Subcellular location: Cell membrane
Pathways (Reactome):
Signal Transduction: Axonal growth inhibition (RHOA activation)
Gene Ontology:
Biological process: neuron projection regeneration
Cellular component: plasma membrane
Genetic constraint (gnomAD): Loss-of-function variants: 9 observed, 27.81 expected, observed/expected ratio (o/e) 0.32, 90% interval 0.19 to 0.56. The upper end of that interval is the gene's LOEUF score, 0.56, which puts it in group 2 of 6, group 1 being the genes least tolerant of losing a copy. Missense variants: 402 observed, 542.31 expected, observed/expected ratio (o/e) 0.74, 90% interval 0.68 to 0.81. Synonymous variants: 179 observed, 202.48 expected, observed/expected ratio (o/e) 0.88, 90% interval 0.78 to 1.
Homologues: Orthologues: chimpanzee OMG (99% identical), macaque OMG (98% identical), dog OMG (96% identical), pig OMG (94% identical), guinea pig OMG (92% identical), rabbit OMG (91% identical), rat Omg (89% identical), mouse Omg (89% identical), tropical clawed frog omg (42% identical), zebrafish omgb (32% identical), zebrafish omga (27% identical). Paralogues in human: PRELP (17% identical), OMD (16% identical), KERA (15% identical), FMOD (14% identical), LINGO3 (14% identical), ECM2 (14% identical), LUM (14% identical), LINGO4 (13% identical), OGN (10% identical), EPYC (10% identical).
Diseases named in the same sentence as OMG in open-access papers:
OMG is named in the same sentence as 34 diseases in open-access papers, as found by Europe PMC text mining. Sharing a sentence is not in itself a finding about the gene and the disease. The quoted sentences say what the papers report.
multiple sclerosis (4 papers, 2020 to 2026). A progressive autoimmune disorder affecting the central nervous system resulting in demyelination. "Oligodendrocyte myelin glycoprotein (OMGP) has been recognized as a novel antigen in central nervous system disorders such as multiple sclerosis and acute disseminated encephalomyelitis." (PMID 40625923, 2025).
intellectual disabilities (2 papers, 2017 to 2024). "Loss-of-function mutations in the OMG gene have not, however, been observed in patients withidiopathic intellectual disability." (PMID 28213670, 2017).
Autoimmunity (1 paper, 2020). The occurrence of an immune reaction against the organism's own cells or tissues. "This study analyzes autoimmunity to oligodendrocyte myelin glycoprotein (OMGP), because this protein is specifically expressed in the CNS and there found on both oligodendrocytes and neurons." (PMID 33256847, 2020).
learning disability (1 paper, 2019). A group of disorders that affect a person's ability to learn or process specific types of information which is in contrast to his/her apparent level of intellect. "Haploinsufficiency of the OMG gene has been proposed to be associated with learning disability." (PMID 31652930, 2019).
leukemia (1 paper, 2014). A malignant (clonal) hematologic disorder, involving hematopoietic stem cells and characterized by the presence of primitive or atypical myeloid or lymphoid cells in the bone marrow and the blood. "Another distinctive feature of the gene is the presence of 3 genes in intron 27b on the antisense strand: OMGP (oligodendrocyte-myelin glycoprotein), a membrane glycoprotein, and EVI2A and EVI2B (ecotropic viral integration sites), which are involved in the development of mouse leukemia." (PMID 25026295, 2014).
macular degeneration (1 paper, 2024). Loss of vision in the central portion of the retina (macula), secondary to retinal degeneration. "In addition, we observed CFHR3 to be associated with macular degeneration, and OMG and ITIH1 to be associated with height." (PMID 38540773, 2024).
neurological disorders (1 paper, 2024). "OMG, LRTM2, GRIK1, and CDH9 are predominantly expressed in the nervous system, participating in neuronal and synaptic functions, has a significant impact on the occurrence of various neurological disorders." (PMID 38979414, 2024).
OMG also shares sentences with these, for which no sentence is quoted: acute disseminated encephalomyelitis (2 papers); amyloid (2); cognitive disorder (2); experimental autoimmune encephalomyelitis (2); glioma (2); autoimmune disease (1); brain tumours (1); central nervous system disorder (1); dementia (1); demyelination (1); developmental delay (1); encephalitis (1); Friedreich ataxia (1); glaucoma (1); Hydrocephalus (1); infection (1); inflammation (1); melanoma (1); meningitis (1); migraine (1); neurodegenerative disease (1); neuromyelitis optica spectrum disorders (1); peripheral nerve injury (1); psychosis (1); Stroke (1); tumor (1); type I diabetes (1).